RAB28 (RAB28, member RAS oncogene family)
Description:
The small GTPases Rab are key regulators of intracellular membrane trafficking, from the formation of transport vesicles to their fusion with membranes. Rabs cycle between an inactive GDP-bound form and an active GTP-bound form that is able to recruit to membranes different sets of downstream effectors directly responsible for vesicle formation, movement, tethering and fusion. RAB28 is required for shedding and phagocytosis of cone cell outer segments (OS) discs in the retina (By similarity). Also participates in nuclear factor kappa-B p65/RELA nuclear transport in endothelial cells (By similarity).
Synonyms: CORD18
Tractability: Small molecule: a structure with a bound ligand is known; it has a binding pocket of medium quality. Antibody: UniProt places it where antibodies can reach, with high confidence; its Gene Ontology location is reachable by antibodies, with medium confidence. PROTAC: ubiquitination databases record sites on it; its protein half-life has been measured.
Gene: Protein-coding gene on chromosome 4 (13,361,354 to 13,484,365, reverse strand). Ensembl gene ENSG00000157869.
Subcellular location: Cell membrane; Cytoplasm, cytoskeleton, cilium basal body; Cytoplasm; Nucleus
Gene Ontology:
Molecular function: G protein activity; GDP binding; GTP binding; protein binding; GTPase activity
Cellular component: ciliary basal body; ciliary rootlet; cytoplasm; nucleus; plasma membrane
Genetic constraint (gnomAD): Loss-of-function variants: 10 observed, 12.72 expected, observed/expected ratio (o/e) 0.79, 90% interval 0.48 to 1.33. The upper end of that interval is the gene's LOEUF score, 1.33, which puts it in group 5 of 6, group 1 being the genes least tolerant of losing a copy. Missense variants: 152 observed, 151.88 expected, observed/expected ratio (o/e) 1, 90% interval 0.88 to 1.14. Synonymous variants: 59 observed, 53.75 expected, observed/expected ratio (o/e) 1.1, 90% interval 0.89 to 1.36.
Homologues: Orthologues: chimpanzee RAB28 (100% identical), macaque RAB28 (99% identical), dog RAB28 (96% identical), pig RAB28 (96% identical), mouse Rab28 (95% identical), guinea pig RAB28 (92% identical), rabbit RAB28 (87% identical). Paralogues in human: RAB6B (34% identical), RAB1A (32% identical), RAB37 (32% identical), RAB6A (32% identical), RAB18 (31% identical), RAB1B (31% identical), RAB26 (31% identical), RAB4A (31% identical), RAB4B (31% identical), RAB8A (31% identical), RAB8B (31% identical), RAB11A (30% identical), and 56 more.
Diseases named in the same sentence as RAB28 in open-access papers:
RAB28 is named in the same sentence as 22 diseases in open-access papers, as found by Europe PMC text mining. Sharing a sentence is not in itself a finding about the gene and the disease. The quoted sentences say what the papers report.
cone-rod dystrophy (12 papers, 2016 to 2025). Inherited retinal dystrophies that belong to the group of pigmentary retinopathies. "RAB28 is an essential gene for vision, and loss of function mutations in RAB28 cause cone-rod dystrophy in humans." (PMID 38902764, 2024). "Rab28 mutations cause cone-rod dystrophy 18 (CRD18) (OMIM #615374), presenting with central retinal atrophy and hyperpigmented appearance of the fovea." (PMID 39026984, 2024). "A similar process is described in murine photoreceptors, in which knock-out of Rab28 leads to elongated and enlarged outer segments, suggesting a disc shedding impairment, explaining the cone-rod dystrophy caused by RAB28 mutations in humans." (PMID 36672247, 2023). "The genotypes of four patients with cone-rod dystrophy, all homozygotes for the newly identified mutation p.(His144Tyr) in the gene RAB28, fit very well into this category." (PMID 36909829, 2023). "To date, six alterations in the RAB28 gene have been associated with autosomal recessive cone-rod dystrophies." (PMID 33396523, 2020). "Our data shed light on RAB28 function in cones and provide a model for RAB28-associated cone-rod dystrophy." (PMID 32258030, 2020). "Mutations in Rab28 have been found to cause two types of cone-rod dystrophy (18 and 6); the molecular mechanism underlying the disease, however, is unclear." (PMID 27832175, 2016). "We present several cilium-localised proteins resulting from our analysis, including RAB-28, a GTPase previously implicated in the degenerative eye disease known as cone-rod dystrophy." (PMID 27930654, 2016). "RAB28, which is a distal member of the Rab family and present in both photoreceptors and RPE, has been associated with nonsense mutations in RAB28, causing cone-rod dystrophy 18, with foveal atrophy and hyperpigmentation and diminished cone and rod responses in humans." (PMID 37510362, 2023). "As small GTPases are good drug targets, it should be feasible to develop a RAB28 inhibitor, however, given the association of RAB28 with cone rod dystrophy, future work is required to determine if chronic treatment with such an inhibitor is a feasible therapeutic option." (PMID 27832175, 2016). "In agreement, a rab28 knockout mouse displays cone-rod dystrophy, resulting from failure of cone outer segment (COS) phagocytosis." (PMID 32258030, 2020). "In PR cells, PrBP/δ traffics prenylated cargo such as PDE6, Rab28, and rhodopsin kinase (GRK1) from the site of protein synthesis (inner segment) to the retinal outer segment, and its homozygous deletion causes slow, progressive rod-cone dystrophy." (PMID 39026984, 2024). "Consistent with a non-essential global requirement for ciliogenesis, IFT and BBSome integrity, patients carrying predicted strong loss-of-function or possibly null alleles in RAB28 do not present with wider ciliopathy symptoms beyond cone-rod dystrophy." (PMID 27930654, 2016). "The Rab28−/− mouse model shows cone responses diminished at 1 month old and nearly absent at 12 months of age, which is consistent with human cone-rod dystrophy." (PMID 37510362, 2023).
autosomal recessive cone rod dystrophy (3 papers, 2016 to 2020). autosomal cone rod dystrophy is an autosomally recessive inherited retinal dystrophy that belongs to the group of pigmentary retinopathies. "Here, we show that the ciliary G-protein Rab28, associated with human autosomal recessive cone-rod dystrophy, negatively regulates EV levels in the sensory organs of Caenorhabditis elegans in a cilia specific manner." (PMID 32101165, 2020). "To date, only mutations in Rab28 have been identified to cause human retina disease (recessive cone-rod dystrophy 18), and defective geranylgeranylation of Rab27 was shown to be linked to choroideremia." (PMID 27529348, 2016). "Further analyses of C. elegans RAB-28, recently associated with autosomal-recessive cone-rod dystrophy, reveal that this small GTPase is exclusively expressed in ciliated neurons where it dynamically associates with IFT trains." (PMID 27930654, 2016). "Both GFP reporters for RAB-28 (driven by bbs-8 gene or endogenous promoter), the orthologue of the small ciliary GTPase RAB28 linked to human autosomal-recessive cone-rod dystrophy, localise along the entire cilium." (PMID 27930654, 2016). "One of the highest ranked hits in our candidate list of ciliary genes is RAB-28, a small GTPase whose human counterpart is linked to autosomal-recessive cone-rod dystrophy and vision impairment." (PMID 27930654, 2016).
retinal degeneration (3 papers, 2020 to 2025). Degeneration of the retina. "Rab28 KO mice exhibit progressive retina degeneration phenocopying the clinical features of CRD." (PMID 40395934, 2025). "Significantly, rab28 null zebrafish display a 40–50% reduction in OS shedding as early as 15 days post fertilization (dpf), but without evidence of retinal degeneration up to 12 mpf." (PMID 32258030, 2020). "The role of Rab-28 in regulating membrane shedding from cone outer segment tips has been confirmed in a RAB28 knockout zebrafish model where, however, a longer visual function with no sign of retinal degeneration up to 12 months has been observed." (PMID 33396523, 2020). "The absence of retinal degeneration in rab28 knockout zebrafish may be the result of this compensatory transcriptional adaptation." (PMID 32258030, 2020). "In contrast to the mouse rab28 knockout, rab28 knockout zebrafish display decreased RPE phagosomes, but normal visual function up to 21 dpf and no retinal degeneration up to 12 mpf." (PMID 32258030, 2020).
polydactyly (2 papers, 2021 to 2025). A disease characterized by the presence of polydactyly, including syndromic and non-syndromic forms. "RAB28 was associated with CRD, in turn associated with polydactyly in a few cases." (PMID 34828430, 2021).
atherosclerosis (1 paper, 2013). A disease characterized by the build-up of fatty material and calcium deposition in the arterial wall resulting in partial or complete occlusion of the arterial lumen. "Understanding of the effects of Rab28 on molecular “switches” and biological function will help to define the molecular mechanisms underlying vascular homeostasis and development of vascular pathologies, such as atherosclerosis, thrombosis, hypertension, as well as their clinical complications." (PMID 23457503, 2013).
Atrophy (1 paper, 2024). Any weakening or degeneration, especially through lack of use. "RAB28 mutations are associated with childhood-onset CORD18 (MIM# 615374), which manifest following reduced BCVA, dyschromatopsia, bull’s eye maculopathy, foveal hyperpigmentation, peripapillary atrophy, extinguished photopic ERG responses, and reduced scotopic ERG responses." (PMID 38892339, 2024).
cone dystrophy (1 paper, 2024). An inherited ocular disorder characterized by the loss of cone cells, the photoreceptors responsible for both central and color vision. "Initial ES analysis identified a heterozygous c.68C>T:p.(Ser23Phe) variant in RAB28 in a patient with cone dystrophy." (PMID 38819824, 2024).
Hypertension (1 paper, 2013). The presence of chronic increased pressure in the systemic arterial system. "To evaluate the mechanism involved in EC functional changes during hypertension, we focus on a novel molecule with potential mechano-sensitivity, Rab28, which was firstly revealed by our previous vascular proteomic study." (PMID 23457503, 2013). "Hence, we hypothesized that Rab28 might be a novel regulator of EC homeostasis and play a significant role in cyclic strain-induced vascular remodeling during hypertension." (PMID 23457503, 2013). "The effects of Rab28 on biological behaviors of vascular cells, especially on EC growth and survival, suggest that the modulations of Rab28 expression might participate in vascular remodeling during hypertension." (PMID 23457503, 2013).
melanoma (1 paper, 2016). A malignant, usually aggressive tumor composed of atypical, neoplastic melanocytes. "WDR5 target RAB28, member of the Ras oncogene family, is reported to be differentially expressed in swine melanoma." (PMID 27192115, 2016).
cancer (1 paper, 2017). A tumor composed of atypical neoplastic, often pleomorphic cells that invade other tissues. "Other MS loci display marked cancer-type specificity, for example, MSI events within the 5′ UTR region of ZNF738, C10orf140, ZNF271 and RAB28 are specific to COAD tumours, whereas those in EBP, TMEM182, MIR567 and MEIS1 are absent or substantially depleted in STAD compared to COAD and UCEC tumours." (PMID 28585546, 2017).
RAB28 also shares sentences with these, for which no sentence is quoted: Bull's eye maculopathy (1 paper); Charcot-Marie-Tooth disease, type 6 (1); choroideremia (1); ciliopathy (1); Dyschromatopsia (1); hereditary corneal dystrophies (1); infection (1); optic atrophy (1); retinal disease (1); Retinal dystrophy (1); retinitis pigmentosa (1); tumours (1).